IL31 (interleukin 31)
Diseases named in the same sentence as IL31 in open-access papers (continued):
Sharing a sentence is not in itself a finding about the gene and the disease.
Pruritus (continued). "Delgocitinib successfully inhibits IL-31-induced pruritus, contributing to the cessation of habitual ear manipulation." (PMID 40568299, 2025). "IL-31 is a well-established therapeutic target, with oclacitinib and lokivetmab effectively reducing pruritus by modulating IL-31-mediated pathways." (PMID 41227548, 2025). "Several cytokines, including TSLP, IL-13, IL-31, and IL-4, are involved in pruritus, one of the most prominent features of AD." (PMID 40429704, 2025). "Interventional trials evaluating how targeted microbial restoration or immune modulation (e.g., topical probiotics, IL-31 inhibitors) impact pruritus severity and microbiome composition would provide mechanistic and clinical insight." (PMID 40869459, 2025). "Lokivetmab, a monoclonal antibody against IL-31 approved for the treatment of canine AD, provides interspecies validation of the IL-31–neural axis in pruritus." (PMID 41235218, 2025). "In the ovalbumin-induced atopic dermatitis model, intrathecal injection of IL-31 has been shown to evoke pruritus in mice, with the IL-31 receptor co-localizing in TRPV1-positive DRG neurons." (PMID 40095628, 2025). "Future investigations should integrate multidimensional pruritus profiling with biomarker stratification (e.g., serum IL-31 levels) to differentiate methodological artifacts (“noise”) from genuine pathophysiological signals in safety outcome assessments." (PMID 41312463, 2025). "Interleukin (IL)-4, IL-13, and IL-31 play crucial roles in pruritus; therefore, their inhibition is a key therapeutic strategy." (PMID 40568299, 2025). "This upregulates IL-31, primarily from Th2 cells, which directly activates sensory neurons to induce pruritus and impairs keratinocyte differentiation." (PMID 41155460, 2025). "IL-31 is strongly implicated in the pathogenesis of PN, and there is a known correlation between IL-31 and HIV related pruritus." (PMID 40491521, 2025). "The dramatic response observed in this patient reinforces the importance of IL-31 in chronic pruritus." (PMID 40491654, 2025). "IL-31 is a T-lymphocyte-derived cytokine that directly stimulates sensory neurons for the generation of pruritus." (PMID 39487054, 2025). "Upon activation by IL-31, these cells secrete various chemokines and inflammatory mediators, which play a role in the pathogenesis of pruritus." (PMID 41166019, 2025). "In the current study, the inhibitory effect of DHS on pruritus was investigated in lipopolysaccharide (LPS)-stimulated microglia, IL-31- and IL-6-treated astrocytes, and chloroquine-treated mice." (PMID 40443235, 2025). "Several factors enable the elongation of peripheral sensory nerves in AD such as IL-31, which induces severe pruritus." (PMID 40677708, 2025). "Pruritus and poikiloderma: Pruritus is common and can be disabling in DM; mechanistic studies implicate the IL-31 axis among pruritogens." (PMID 41441445, 2025). "Th2 cytokines such as interleukin (IL)-4, IL-13, and IL-31 promote inflammation and pruritus, whereas regulatory cytokines including transforming growth factor-β1 (TGF-β1) help preserve immune homeostasis." (PMID 41227548, 2025). "In human AD, IL-4 and IL-13 promote IgE synthesis and barrier dysfunction, IL-31 induces pruritus via neuronal activation, and TGF-β1 mediates regulatory control." (PMID 41227548, 2025). "Among these, IL-31 is a critical mediator of pruritus and eosinophilic inflammation that impairs skin barrier function." (PMID 41155460, 2025). "This activates polyclonal T cells, triggering massive release of IL-31 (directly inducing pruritus) and IFN-γ (driving chronic inflammation)." (PMID 40771817, 2025). "Type 2 cytokines, such as interleukin (IL)-4, IL-13, and IL-31, play central roles in promoting skin barrier disruption, suppressing antimicrobial peptides, and inducing pruritus." (PMID 40566057, 2025). "Produced by activated CD4+ Th2 cells, IL-31 activates the DRG via receptors on C-fiber nerve terminals in the skin to elicit pruritus." (PMID 40677708, 2025).
Pruritus (continued). "Emerging data also suggest a role for IL-31 in contributing to pruritus and sensory nerve sensitization in CSU, although its precise function requires further elucidation." (PMID 41226755, 2025). "Elevated serum IL-31 levels have been reported in both PN and dialysis-related pruritus, suggesting a shared pathophysiological role of IL-31 in these conditions." (PMID 40458322, 2025). "Subsequently, the actions of IL-4 and IL-13 drive the production of IgE, whereas IL-31 induces pruritus." (PMID 39717308, 2024). "Dogs treated with the plant-made M1 mAb obtained identical or even slightly better control of IL-31-induced pruritus compared to Lokivetmab-treated ones after challenge with canine IL-31." (PMID 38932349, 2024). "Coix sprouts extract reduced the expression of IL-31, a biomarker of histamine-independent pruritus." (PMID 39519379, 2024). "In our study, we observed elevated serum levels of IL-31 in MF patients with pruritus and the levels correlated with itch intensity." (PMID 39068637, 2024). "This supports previous findings that malignant CD4 + T cells obtained from CTCL patients can produce IL-31, and its levels correlate with pruritus severity in advanced stages of the disease." (PMID 39068637, 2024). "IL-31 is a recently identified cytokine with a well-defined role in the pathogenesis of pruritus and is produced predominantly by circulating Th2 lymphocytes." (PMID 38398754, 2024). "MTX in subjects with moderate/severe AD reduced epidermal hyperplasia and altered the expression of inflammatory cytokines and receptors that are related to pruritus, including IL-31 and IL-31RA." (PMID 37730501, 2024). "IL-31 is a key player in the pathogenesis of pruritus, both in the acute and in the chronic stages, and its signaling pathway is closely regulated by IL-4 and IL-13." (PMID 38398754, 2024). "The inhibitory effect of the Coix sprouts extract on the generation of IL-31, a key substance in histamine-independent pruritus induction, was also examined." (PMID 39519379, 2024). "Similar results were obtained with piperine, which also prevented MCs degranulation to LL-37, but also reduced IL-31 secretion, which has been proposed as a key clinical target for the treatment of pruritus." (PMID 38535499, 2024). "Especially, IL-31, which is mainly released from activated Th2 cells, induces pruritus and lichenification during the development of AD." (PMID 38386273, 2024). "Epidermal keratinocytes have been reported to mediate IL-31-induced pruritus through the secretion of pruritogenic stimulators when stimulated by IL-31 through its receptor complex." (PMID 38493053, 2024). "A positive correlation was observed between the serum levels of IL-17 and the severity of the disease, as well as between the serum levels of IL-31 and the severity of pruritus." (PMID 38541037, 2024). "Interleukin-31 (IL-31) has emerged as a significant mediator of pruritus by activating sensory neurons." (PMID 39598548, 2024). "Only dogs with pruritus values after IL-31 challenge (at D-20, D-14, and D-7) equivalent to twice the average of the basal values (evaluated at D-23 and D-22) and in good health were included in the study." (PMID 38932349, 2024). "In summary, IL-31 plays a crucial role in the pathophysiology of human AD, particularly in its role in pruritus, highlighting its importance in the condition." (PMID 38590314, 2024). "This implication of IL-31 in pruritus and the promotion of scratching behavior was further corroborated in Nishiki-nezumi Cinnamon/Nagoya (NC/Nga) mice with dermatological lesions, serving as a model for AD." (PMID 38590314, 2024). "Th2-related peripheral pruritus mediated by IL-31 acting on the specific receptor IL-31Ra on peripheral nerves and other immune cells such as eosinophils seemed to be involved and was associated with a more severe disease presentation." (PMID 39076967, 2024).
Pruritus (continued). "When IL-31 is injected or overexpressed pruritus is provoked and the neural growth of neurons with a small diameter is selectively promoted which activates several of the same genes as a nerve growth factor." (PMID 36983094, 2023). "When mice experience an itch, e.g., when IL-31 is injected intradermally, they elicit over 1.0 s lasting scratching behavior (LLS)." (PMID 37511321, 2023). "IL-31 belongs to the IL-6 cytokine family, which can directly trigger pruritus in humans and is called “itch cytokine”." (PMID 38077377, 2023). "IL-31Rα is also expressed in sensory nerves and IL-31 promotes nerve fiber extension, suggesting that IL-31 is involved in pruritus in AD." (PMID 37881433, 2023). "It is not currently being investigated for the treatment of psoriasis, but if the role of IL-31 in the pathogenesis of this disease becomes more established, nemolizumab could also be evaluated as a therapeutic option for the treatment of psoriasis-associated pruritus." (PMID 37509136, 2023). "Pruritus induced by IL-31 is mediated by directly activating IL-31RA on the cutaneous TRPV1+ sensory nerve." (PMID 36874007, 2023). "Recognizing IL-31’s implication in pruritus and its relevance in AD and other allergic conditions has fostered its consideration as a therapeutic target." (PMID 37762898, 2023). "Our findings revealed a significant association between IL-31 levels in CSU patients and pruritus intensity, disease severity, and quality of life." (PMID 37762898, 2023). "Th2 cytokines IL-4, IL-13, and IL-31, which play also a crucial role in eosinophil chemoattraction, maturation and activity, and induction of pruritus, have been shown to increase both in the peripheral blood and skin lesions of BP patients." (PMID 36814775, 2023). "Distinguishing itself from prior research centered on IL-31’s role in pruritus, inflammation, and immune modulation, our study specifically delves into IL-31’s involvement within the context of CSU." (PMID 37762898, 2023). "Interleukin-31 (IL-31), a possible mediator of itching, induces severe pruritus and dermatitis in mice." (PMID 37511321, 2023). "Since IL-31 also induces nerve sprouting, IL-31 bridges the gap between immune cells and the nervous system, indicating neuroimmune interaction mechanisms that lead to an early priming of pruritus." (PMID 36979421, 2023). "IL-31 is one of the main cytokines involved in the pathogenesis of pruritus in atopic dermatitis in different species." (PMID 37993920, 2023). "The reduction in IL-31 levels during irradiation appears to correspond with a decrease in pruritus, suggesting a significant role of IL-31 in the pathogenesis of psoriatic pruritus." (PMID 37834183, 2023). "The substantial correlations uncovered in this study contribute to the growing body of evidence highlighting IL-31’s potential as a key player in pruritus etiology and severity." (PMID 37762898, 2023). "IL‐31 is a pro‐inflammatory cytokine of the IL‐6‐derived cytokine family, whose levels are highly correlated with itch severity." (PMID 36789100, 2023). "To investigate the role of IL-31 signaling in CTCL-induced itch in mice, we conducted ISH, ELISA, and behavioral analyses." (PMID 36520531, 2023). "For the first time, a direct correlation between memory T-cell-derived IL-31 response to HDM in vitro and patient’s pruritus was demonstrated, which underlines the clinical relevance of this mechanism in AD." (PMID 36993985, 2023). "Epidermal IL-31 levels correlated with itch severity in patients with CTCL with moderate-to-severe pruritus." (PMID 36520531, 2023). "A correlation between IL-31 production and patient’s pruritus intensity, plasma CCL27 and periostin was detected." (PMID 36993985, 2023). "In addition, IL-31 may act directly on the peripheral nerve, causing the pruritus related to AD." (PMID 37686326, 2023). "Pruritus is a major symptom in BP, suggesting a possible involvement of the pruritogenic cytokine IL-31." (PMID 37509055, 2023).
Pruritus (continued). "In PN lesions, this receptor is also notably increased, and the intensity of pruritus in PN is closely related to the number of IL-31+ cells and IL-31Rα+ cells in the dermis." (PMID 38077377, 2023). "Our initial intention was to assess every itch behavior in our IL-31 study and quantify the duration in seconds." (PMID 37235412, 2023). "Within group 1 of patients, HDM-induced IL-31 response directly correlated with pruritus (r = 0.67, p = .0036) and plasma levels of CCL27 (r = 0.62, p = .0090) and periostin (r = 0.56, p = .050)." (PMID 36993985, 2023). "Pruritus, the key symptom of AD, has substantial participation of the IL-31 complex and activation of relevant signaling pathways." (PMID 36839897, 2023). "Interleukin-31 (IL-31) is a possible mediator of itching that induces severe pruritus and dermatitis in mice." (PMID 38003738, 2023). "In recent years, more and more attention has also been directed toward understanding the role of interleukin-31 (IL-31) in pruritus." (PMID 37834183, 2023). "In group 1, compared with group 2, HDM-induced IL-31 in CLA+ T cells positively correlated with patient ́s pruritus intensity, and plasma levels of CCL27 and periostin." (PMID 36993985, 2023). "According to a recent study, IL-4 increased IL-31/IL-31 receptor signaling, which is crucial for the pathophysiology and transmission of pruritus in AD." (PMID 36983094, 2023). "Vaccination against IL-31 was assessed for its effectiveness in reducing pruritus in horses with IBH." (PMID 37570323, 2023). "The advanced stages of CTCL, with typical severe pruritus, shift toward a predominant Th2-cell microenvironment releasing cytokines such as IL-4, IL-5, or IL-31 that have gained attention in other itching inflammatory disorders." (PMID 37874473, 2023). "JAK inhibitors are anticipated to have therapeutic prospects in BP as pruritus and inflammatory skin lesions are both important features of BP, and there is increased expression of Th2 cytokines, such as IL-4, IL-5, IL-13, and IL-31, in BP patients." (PMID 37614956, 2023). "IL-31, a member of the gp130/IL-6 family with an anti-parallel four-helix bundle structure, plays a key role in inducing pruritus in different diseases, such as atopic and contact dermatitis, psoriasis and chronic urticaria." (PMID 37509136, 2023). "Interleukin-31 (IL-31) has been found to be one of the main initiators of pruritus in dogs with allergic dermatitis." (PMID 35928119, 2022). "Nemolizumab was developed as an inhibitor of IL-31 signaling, and several studies have presented findings that indicated a direct effect of IL-31 in the generation of pruritus in patients with atopic dermatitis." (PMID 35558086, 2022). "Overexpression of IL-31 potently induces pruritus and promotes elongation and branching of sensory nerve fibers, thereby increasing the intensity of AD symptoms." (PMID 35889539, 2022). "Interleukin-31 (IL-31) is a T-cell-derived cytokine that takes part in the symptomatology of pruritus, and both IL-31 and its receptor have become potential therapeutic targets for a range of pruritic disorders." (PMID 35324695, 2022). "Lenabasum (JBT-101, anabasum), a selective cannabinoid receptor type 2 agonist, downregulated the expression of IL-31 from CpG stimulated peripheral blood mononuclear cells in an in vitro study, suggesting a possible role in treatment of DM-related pruritus." (PMID 35885674, 2022). "Performed studies revealed a positive correlation between the IL-31 serum level and the Scoring Atopic Dermatitis Index (SCORAD) and also between IL-31 levels and the severity of pruritus-." (PMID 35324695, 2022). "Although the pleiotropic role of IL-31 has been studied in several diseases, the most prominent role is represented by the pathogenesis of pruritus, especially in skin conditions such as atopic dermatitis (AD)." (PMID 35742951, 2022).
Pruritus (continued). "Firstly, IL-31 has been studied in patients affected by atopic dermatitis, in which this cytokine is the major promoter of pruritus and scratching behavior." (PMID 35742951, 2022). "The expression and release of IL-31 induced by IL-4 in Th2 cells are a recently identified cytokine with a well-defined role in the pathogenesis of pruritus." (PMID 35563259, 2022). "These reactions involve a myriad of different cytokines including interleukin-31 (IL-31) which has been found to be one of the main inducers of pruritus in dogs with atopic dermatitis." (PMID 35928119, 2022). "Based on its roles in the development of itch, skin deficits, and inflammation, targeting the IL-31 pathway is a logical step in the development of new pharmacologic agents against pruritus." (PMID 33644103, 2021). "Lokivetmab (ZTS-00103289) is a caninized IL-31 monoclonal antibody that has demonstrated efficacy in reducing pruritus in dogs, in various conditions including atopic dermatitis, and mastocytosis." (PMID 33644103, 2021). "Previous studies have indicated that IL-31, IL-4Rα, JAK1, and HRH4 are strongly associated with pruritus in AD." (PMID 34970141, 2021). "qPCR analyses resulted in lowly expressed IL31 expression levels in 4 of 8 patients; these patients all suffered from pruritus and advanced stage disease." (PMID 34027133, 2021). "Interleukin 31 has been reported to play a role in the etiology of pruritus, chronic inflammation and regulation of innate and adaptive immunity in tissues exposed to environmental factors." (PMID 33401724, 2021). "In this condition, the intensity of pruritus is correlated with the numbers of dermal IL-31+ cells and dermal IL-31RA+ cells." (PMID 33924978, 2021). "In recent years, the published literature has suggested the key involvement of the cytokine interleukin-31 (IL-31) in the symptomatology of pruritus, and both IL-31 and its receptor have become potential therapeutic targets for a range of pruritic diseases." (PMID 33644103, 2021). "Its role in the mediation of pruritus has gained attention, but it important to emphasize that IL-31 also modulates keratinocyte proliferation and differentiation." (PMID 34357916, 2021). "Investigation in animal models suggested a role for IL-31 in the cutaneous and epithelial signs and symptoms observed in pruritus, skin inflammation, and airway hypersensitivity." (PMID 33644103, 2021). "Experiments revealed that IL-31 induces pruritus by binding to IL-31RA that is exclusively expressed on TRPV1+/TRPA1+ DRG neurons indicating TRP channels as key mediators of T-cell mediated IL-31-induced pruritus." (PMID 33681256, 2021). "One of the prime distinguishing aspects of IL-31 is that it induces late onset pruritus, in contrary with the immediate histamine-induced pruritus." (PMID 35386968, 2021). "In one analysis, levels of IL-31 mRNA appeared to be correlated with the severity of pruritus in CTCL patients, although data from another study did not support this contention." (PMID 33644103, 2021). "Recent studies suggested a role for IL31 in the pathogenesis of pruritus and disease severity in patients with cutaneous T cell lymphomas (CTCL)." (PMID 34027133, 2021). "Recent studies have elucidated a close relationship of pruritus with IL-31, which is produced by Th2 cells, macrophages, dendritic cells and eosinophils." (PMID 33924978, 2021). "Evaluating IL-31 role in pruritus pathogenesis have to necessarily consider both the plasmatic interleukin and its relative receptors: IL-31 receptor A and the oncostatin M receptor." (PMID 34118946, 2021). "IL-31 induces pruritus by initiating the transduction (act as pruritogens) and sensitizes the TRP channels, thereby worsen the itch condition." (PMID 34276687, 2021). "Over the past years, IL31 has been reported to play a central role in the pathogenesis of pruritus and an IL31 receptor antagonist is being developed as a novel therapeutic strategy for the reduction of pruritus in AD patients." (PMID 34027133, 2021).